EGFR (epidermal growth factor receptor)
Diseases named in the same sentence as EGFR in open-access papers (continued):
Sharing a sentence is not in itself a finding about the gene and the disease.
nasopharyngeal carcinoma (continued). "In nasopharyngeal carcinoma, EGFR expression rate was as high as 90%, and it was closely related to chemoresistance, radioresistance and poor prognosis." (PMID 33875643, 2021). "NMHC IIA expression increased the invasion and metastasis abilities of the nasopharyngeal cancer cell line in vitro by augmenting the expression of phosphorylation of EGFR, AKT and ERK." (PMID 34093822, 2021). "In summary, the addition of concurrent chemotherapy can significantly improve the survival outcome of stage II-IVb nasopharyngeal carcinoma patients treated with concurrent anti-EGFR agents." (PMID 34976847, 2021). "As is the situation for molecular targeted drugs, EGFR-targeted therapy has been anticipated to be effective for nasopharyngeal cancer, and drugs that are specific to nasopharyngeal cancer (e.g., nimotuzumab) are being investigated." (PMID 35006440, 2021). "In summary, this study showed that UC2288 decreased cell proliferation and induced apoptosis in nasopharyngeal carcinoma cells through inhibition of EGFR/ERK pathway." (PMID 33442398, 2021). "Studies have shown that LMP1 mediates the expression of the EGFR in nasopharyngeal carcinoma in several ways, including via the NF-κB pathway and STAT3 activation." (PMID 34578147, 2021). "Meanwhile, as EGFR has been reported as an important regulator of VM in various malignancies, we considered that VM may be the main leading cause that is associated with the difference in efficacy of anti-angiogenic drugs and anti-EGFR drugs in nasopharyngeal carcinoma." (PMID 33875643, 2021). "In nasopharyngeal carcinoma, hsa_circRNA-006660 was confirmed to target EGFR through the modulation of miR-1276." (PMID 33335643, 2020). "Promising approaches are for example the combinations of Src-inhibitor dasatinib with EGFR-inhibitor afatinib in TNBC or DDR1-inhibitor 7rh in nasopharyngeal carcinoma." (PMID 32668815, 2020). "In a study by Chua DT EGFR was shown to be expressed in 89% of nasopharyngeal carcinoma cases, and high EGFR expression is considered an independent prognostic factor for local control, non-recurrence and disease-related survival in stage III-IV NPC." (PMID 31888551, 2019). "The expression rate of epidermal growth factor receptor (EGFR) in nasopharyngeal carcinoma is 68–89%, which is much higher than that of other solid tumors." (PMID 31888551, 2019). "Previous studies have reported that knockdown of PDE4D resulted in EGFR/PI3K/AKT signaling inactivation in nasopharyngeal carcinoma cells." (PMID 31772658, 2019). "Effective Akt inhibition by nimotuzumab had also previously been reported in other cell lines including EGFR overexpressing U87 GB cells, lung and nasopharyngeal carcinoma cells." (PMID 30129426, 2018). "Theoretically, the use of cetuximab to block EGFR has inhibitory effects in most of the nasopharyngeal carcinomas." (PMID 29973197, 2018). "Cetuximab targeted epidermal growth factor receptor (EGFR) for the treatment of nasopharyngeal carcinoma." (PMID 29973197, 2018). "EGFR signaling plays an important role in regulating and maintaining cancer stem cells (CSCs) in nasopharyngeal carcinoma." (PMID 28423495, 2017). "DLC-1 (Loss of deleted in liver cancer-1) induced mitochondrial apoptosis, and inhibited EMT in nasopharyngeal carcinoma by targeting the EGFR/Akt/NF-κB pathway." (PMID 26636541, 2016). "Anti-EGFR monoclonal antibodies and EGFR tyrosine kinase inhibitors have been proven to efficiently inhibit the proliferation of cancers, especially colorectal and nasopharyngeal cancers." (PMID 24618737, 2014). "Recently, we demonstrated that activation of EGFR increased cancer stem-like cell properties in nasopharyngeal carcinoma, and this effect of EGFR was mediated by PI3K/AKT/β-catenin signaling." (PMID 23648139, 2013). "The relationship of EGFR levels to the prognosis in unresectable pharyngeal or nasopharyngeal cancer patients treated by chemo-radiotherapy was recently reported." (PMID 15967033, 2005).
nasopharyngeal carcinoma (continued). "Approximately 80% of nasopharyngeal carcinoma (NPC) patients exhibit EGFR overexpression." (PMID 39820491, 2025). "API was shown to reduce levels of p-EGFR, p-Akt, and p-Stat3 in nasopharyngeal carcinoma." (PMID 38263290, 2024). "It is suggested that serum CD109+ and EGFR+ EVs could be used as biomarkers for nasopharyngeal cancer." (PMID 36968209, 2023). "A study showed that the positive rate of EGFR expression in primary nasopharyngeal carcinoma and metastatic lymph nodes was 73.3% and 60.5%, respectively, and the difference in the expression level between primary and positive lymph nodes was statistically significant (P=0.001)." (PMID 36814816, 2023). "A study showed that EGFR is highly expressed in 80%-90% of nasopharyngeal cancers." (PMID 36814816, 2023). "Additionally, nasopharyngeal carcinoma cells also express a lower level of EGFR and are, therefore, resistant to EGFR inhibition treatment." (PMID 36012290, 2022). "Here, a systematic review and meta-analysis was designed to probe into the correlation between the prognosis of nasopharyngeal carcinoma and the expression of EGFR/p-EGFR, in an attempt to identify the prognostic effect of EGFR/p-EGFR level in nasopharyngeal carcinoma." (PMID 35060503, 2022). "These may be the confounding factors when analyzing the prognostic effect of EGFR expression on the DMFS of nasopharyngeal carcinoma patients." (PMID 35060503, 2022). "Since significant heterogeneity was detected in the meta-analysis of the studies on the association of EGFR expression with OS and DMFS in nasopharyngeal carcinoma patients, we performed sensitivity analysis to see if the exclusion of any study would impact the synthesized results of HR and 95% CI." (PMID 35060503, 2022). "Nasopharyngeal carcinoma has positive expression of EGFR on the tumor cells nucleus." (PMID 35600653, 2022). "Additionally, none of the three studies has performed a systematic review or meta-analysis into the prognostic effect of p-EGFR expression toward nasopharyngeal carcinoma." (PMID 35060503, 2022). "In nasopharyngeal carcinoma patients, EGFR overexpression could be used as a biomarker that predicts poor OS and DFS, but not a prognostic biomarker for PFS and DMFS." (PMID 35060503, 2022). "In addition, we analyzed the prognostic factors of stage II-IVb nasopharyngeal carcinoma patients treated at the Sun Yat-sen University Cancer Center with concurrent anti-EGFR targeted therapy to confirm the findings from the matching cohort." (PMID 34976847, 2021). "In vivo, Foxq1 promoted the growth and metastasis of nasopharyngeal carcinoma, which could be prevented by EGFR inhibitors." (PMID 33875643, 2021). "Therefore, Ag/C225 nanocomposites, as a specific radiosensitizer, exhibited better anti-proliferative effects in nasopharyngeal carcinoma cell lines by assistive EGFR-targeting of C225." (PMID 34322025, 2021). "For examples, studies have shown that β-catenin plays a decisive role in nasopharyngeal carcinoma stem cells through the regulation of the EGFR / AKT gene, and overexpression of β-catenin has been considered as a biomarker of epithelial–mesenchymal transition (EMT) in prostate stem cells." (PMID 30046596, 2018). "Exosomes contain the biological proteins epidermal growth factor receptor (EGFR) and phosphoinositide 3‐kinase (PI3K), which, when activated by protein kinase B (AKT) and extracellular signal‐regulated kinase (ERK) signaling pathways, cause nasopharyngeal cancer cells to undergo carcinogenesis." (PMID 39558933, 2024). "This study aimed to investigate the short-term efficacy and safety of induction chemotherapy (IC) combined with PD-1 inhibitor or anti-EGFR in the treatment of locoregionally advanced nasopharyngeal carcinoma (LA-NPC)." (PMID 37152052, 2023). "The overexpression of p-EGFR was not shown to be associated with the prognosis of nasopharyngeal carcinoma patients and could not be used as a prognostic biomarker." (PMID 35060503, 2022).
nasopharyngeal carcinoma (continued). "The TEV proteins, CD109, and epidermal growth factor receptor (EGFR) are present in nasopharyngeal carcinoma (NPC), and all markers decrease significantly after radiotherapy, suggesting their role in NPC diagnosis." (PMID 35164379, 2022). "Two core networks were generated by hub gene screening using the MCODE plugin of Cytoscape, and AKT1, CTNNB1, HSP90AA1, ESR1, CCND1, and EGFR were identified as key hub proteins, which may play an important role in the efficacy of icaritin in the treatment of nasopharyngeal carcinoma." (PMID 36467051, 2022). "Our previous studies have revealed that EGFR mutations could up-regulate the expression of PD-L1 via p-ERK1/2/p-c-Jun pathways, while LMP-1, an important oncogene in nasopharyngeal carcinoma could also induce the expression of PD-L1 through STAT3, AP-1, and NF-κB pathways." (PMID 26361045, 2015). "Similar to our results, the efficacy of Zn-BC-AM-PDT was increased in nasopharyngeal carcinoma cells (NPC) through the inhibition of EGFR/PI3K/Akt and EGFR/MEK/ERK signaling pathways using an EGFR inhibitor AG1478." (PMID 25918252, 2015). "In nasopharyngeal carcinoma (HONE1 and CNE2) cells, apigenin inhibits drug resistance by suppressing epidermal growth factor receptor (EGFR) signaling." (PMID 40490812, 2025). "In nasopharyngeal carcinoma, SPINK6 activates EGFR and downstream AKT pathway through a similar domain to EGF, enhancing EMT and thus promoting tumor metastasis." (PMID 39990675, 2025). "To assess the efficacy and safety of the combination of immune checkpoint inhibitors (ICIs) and target therapy (anti-angiogenesis or EGFR inhibitors) as a second-line or subsequent treatment for recurrent or metastatic nasopharyngeal carcinoma (R/M NPC), we conducted a retrospective study." (PMID 38242940, 2024). "Cytokines such as IL-6, IL-8, IP-10, TNF-α, VEGF, EGFR, and MIP-3α were found to be elevated in nasopharyngeal carcinoma." (PMID 35964134, 2022). "In the present study, we investigated the relationship between eEF-2 kinase and lapatinib, a dual inhibitor of EGFR and HER-2, in nasopharyngeal carcinoma (NPC) cells." (PMID 27756261, 2016). "Nuclear accumulation of epidermal growth factor receptor (EGFR) and activation of STAT3 by IL-6 play a key role in iNOS expression and resultant DNA damage, leading to EBV-related nasopharyngeal carcinoma." (PMID 25547488, 2014). "MRG003 has already shown encouraging outcomes, following results of another phase I trial, when used in the treatment of patients with EGFR positive refractory advanced squamous cell carcinomas of the head and neck (SCCHN), nasopharyngeal carcinoma (NPC), and colorectal cancer (CRC)." (PMID 39409965, 2024). "p-EGFR was not correlated with the OS of nasopharyngeal carcinoma patients (HR = 1.01, 95% CI [0.88, 1.15], P = .92)." (PMID 35060503, 2022). "This study showed that high EGFR expression was not strongly correlated with the PFS of patients with nasopharyngeal carcinoma." (PMID 35060503, 2022). "For studies that reported PFS, EGFR overexpression was not correlated with the PFS of nasopharyngeal carcinoma patients (HR = 1.86, 95% CI [0.90, 3.82], P = .09)." (PMID 35060503, 2022). "The present study results were in agreement with the three existing systematic review and meta-analyses and suggested that overexpressed EGFR could act as a biomarker of unfavorable OS and DFS in nasopharyngeal carcinoma patients." (PMID 35060503, 2022). "For studies that reported DMFS, EGFR overexpression was not correlated with the DMFS of nasopharyngeal carcinoma patients, and high heterogeneity between studies was detected (I2 = 97%, P < .01)." (PMID 35060503, 2022).
nasopharyngeal carcinoma (continued). "Additionally, nasopharyngeal carcinoma cells (CNE-2), which express a high level of FTH1 and a low level of EGFR, are insensitive to ferroptosis induction and EGFR inhibition." (PMID 36012290, 2022). "Since only one study including 107 nasopharyngeal carcinoma tissue samples investigated the association of p-EGFR and PFS in patients with nasopharyngeal carcinoma, the meta-analysis was not performed." (PMID 35060503, 2022). "This strategy effectively increased intracellular accumulation in nasopharyngeal carcinoma cells with the help of selenium nano-platform and thus sheds light on its application in anti-EGFR therapy." (PMID 34322025, 2021). "As a potential ligand of EGFR, EGFL6 could downregulate the expression of E-cadherin, upregulate the expression of F-actin and Vimentin, and promote metastasis of nasopharyngeal carcinoma through the EMT signal pathway." (PMID 32983976, 2020). "This study inventively combines epidermal growth factor receptor (EGFR) expression of the primary lesion and standardized uptake value (SUV) of positron emission tomography and computed tomography (PET/CT) to predict the prognosis of nasopharyngeal carcinoma (NPC)." (PMID 36814303, 2023). "The overexpression of p-EGFR was not shown to have implications in the prognosis of nasopharyngeal carcinoma patients, thus it could not be used as a biomarker for the prognosis." (PMID 35060503, 2022). "Little is known about the prognostic difference of anti-EGFR therapy, cetuximab (CTX) or nimotuzumab (NTZ), concurrently with induction chemotherapy (IC, investigational arm) or RT (control arm) for patients with locoregionally advanced nasopharyngeal carcinoma (LA-NPC)." (PMID 29580204, 2018). "Anti-EGFR therapy (Nimotuzumab) plus CCRT in the treatment of LA-NPC and anti-PD-1/PD-L1 immunotherapy combined with chemotherapy in the treatment of refractory for recurrent or metastatic nasopharyngeal carcinoma (RM-NPC) have made significant progress." (PMID 37152052, 2023). "Studies of nasopharyngeal carcinoma have further demonstrated a correlation between high EGFR49 expression and poor OS, but not with p-EGFR." (PMID 40738059, 2025). "This systematic review and meta-analysis showed that EGFR overexpression predicted worse OS and DFS of patients with nasopharyngeal carcinoma, but was not correlated with the PFS or DMFS." (PMID 35060503, 2022). "Knock-down of activated leukocyte cell adhesion molecule (ALCAM) results in a reduction in EGFR phosphorylation and MAPK activation in nasopharyngeal carcinoma CNE-2R cells in the absence of EGF, suggesting that ALCAM also maintains the ligand-independent activity of EGFR." (PMID 39594667, 2024). "Overexpressed EGFR could be used as a prognostic biomarker for unfavorable OS and DFS but not DMFS in patients with nasopharyngeal carcinoma." (PMID 35060503, 2022). "Phase I trials for MRG003 were completed for patients with EGFR-positive tumors (NCT04868344), and reasonable objective response rates (ORRs) were observed for HNSCC (40%) and nasopharyngeal carcinoma (NPC; 44%), although not for CRC patients (0%)." (PMID 39065587, 2024).
asthma (106 papers, 2008 to 2026). "In contradiction to the pharmacological EGFR inhibition reports in experimental asthma models, the airway epithelial cell-specific EGFR deficiency resulted in an enhanced MCM in Tg+ mice, a trend consistent with the increased mucus obstruction in these mice." (PMID 40406132, 2025). "Dysregulated EGFR signaling is associated with the pathogenesis of airway hypersecretory and mucoinflammatory diseases such as asthma and COPD." (PMID 40406132, 2025). "The EGFR signaling is implicated in the pathogenesis of airway hypersecretory and mucoinflammatory diseases such as asthma and COPD." (PMID 40406132, 2025). "EGFR has been recognized as a key pathogenic factor and potential therapeutic target in asthma, and its expression increases in response to sustained airway inflammation, leading to epithelial damage in asthmatic airway epithelium." (PMID 35572723, 2022). "Impaired EGFR signaling has also been linked with excessive goblet cell differentiation in asthma and increased mucin expression in CF." (PMID 34248677, 2021). "The EGFR is upregulated in the diseased airway epithelium and aberrant EGFR signaling has been implicated in the pathogenesis of asthma, COPD and CF." (PMID 33868294, 2021). "We and others have also recently reported in animal models, and in clinical studies, that increased EGFR activity is associated with the asthma phenotype." (PMID 31675376, 2019). "In rodent models EGFR inhibition caused decreased lung inflammation from mechanical ventilation and LPS exposure, and airway mucous cell proliferation in asthma models." (PMID 30005089, 2018). "Together, these data suggest that upregulation of EGFR signaling in the context of HDM exposure plays a causal role in the development of asthma-related traits." (PMID 29367592, 2018). "In our asthma model, enhanced EGFR signaling was also associated with increased signaling via, ERK1/2, PI3Kδ/Akt and the transcriptional factor NFκB." (PMID 28855674, 2017). "The effects of TGF-α occur through activation of the epidermal growth factor receptor, which is implicated in numerous chronic respiratory diseases, including lung fibrosis, cancer, chronic obstructive pulmonary disease, asthma and cystic fibrosis." (PMID 28473708, 2017). "Dysregulation of EGFR signaling has been implicated in the pathogenesis of asthma." (PMID 38178132, 2024). "Epithelial growth factor (EGF)-mediated activation of EGFR has already been implicated in disorders with increased immunoreactivity, including asthma, in which Th17 cells may play an important pathogenic role." (PMID 31744223, 2019). "Previous research has shown that the EGFR plays a crucial role in asthma-related airway inflammation and remodeling, and is closely linked to airway thickness and airway hyperresponsiveness (AHR)." (PMID 41599256, 2026). "Investigations have noted the overexpression of multiple EGFR mediators in conditions such as asthma and COPD." (PMID 40136649, 2025). "For instance, decreasing the expression of miR-145 increased the expression of epidermal growth factor receptor (EGFR), which regulates mucin 5AC (MUC5AC), and its overexpression in asthma was linked to pathological mucus hypersecretion." (PMID 41156032, 2025). "Epidermal Growth Factor Receptor (EGFR), was significantly upregulated in severe asthma but significantly decreased in bronchial epithelial cells in COPD." (PMID 40160461, 2025). "Preclinical studies have demonstrated that EGFR inhibitors, including erlotinib and gefitinib, can decrease airway inflammation and airway hyperresponsiveness in animal models of asthma." (PMID 38178132, 2024). "In contrast, an asthma model in mice induced by OVA showed that the expression of miR-145-5p led to less airway remodeling by regulation of EGFR compared with asthmatic mice with inhibited miR-145-5p." (PMID 38337625, 2024).